NR3C1 (nuclear receptor subfamily 3 group C member 1)
Description:
Receptor for glucocorticoids (GC). Has a dual mode of action: as a transcription factor that binds to glucocorticoid response elements (GRE), both for nuclear and mitochondrial DNA, and as a modulator of other transcription factors. Affects inflammatory responses, cellular proliferation and differentiation in target tissues. Involved in chromatin remodeling. Plays a role in rapid mRNA degradation by binding to the 5' UTR of target mRNAs and interacting with PNRC2 in a ligand-dependent manner which recruits the RNA helicase UPF1 and the mRNA-decapping enzyme DCP1A, leading to RNA decay. Could act as a coactivator for STAT5-dependent transcription upon growth hormone (GH) stimulation and could reveal an essential role of hepatic GR in the control of body growth (By similarity). [Isoform Alpha]: Has transcriptional activation and repression activity. Mediates glucocorticoid-induced apoptosis. Promotes accurate chromosome segregation during mitosis. May act as a tumor suppressor. May play a negative role in adipogenesis through the regulation of lipolytic and antilipogenic gene expression (By similarity). [Isoform Beta]: Acts as a dominant negative inhibitor of isoform Alpha. Has intrinsic transcriptional activity independent of isoform Alpha when both isoforms are coexpressed. Loses this transcription modulator function on its own. Has no hormone-binding activity. May play a role in controlling glucose metabolism by maintaining insulin sensitivity (By similarity). Reduces hepatic gluconeogenesis through down-regulation of PEPCK in an isoform Alpha-dependent manner. Directly regulates STAT1 expression in isoform Alpha-independent manner. [Isoform Alpha-2]: Has lower transcriptional activation activity than isoform Alpha. Exerts a dominant negative effect on isoform Alpha trans-repression mechanism. [Isoform GR-P]: Increases activity of isoform Alpha. [Isoform Alpha-B]: More effective than isoform Alpha in transcriptional activation, but not repression activity. [Isoform 10]: Has transcriptional activation activity. [Isoform Alpha-C1]: Has transcriptional activation activity. [Isoform Alpha-C2]: Has transcriptional activation activity. [Isoform Alpha-C3]: Has highest transcriptional activation activity of all isoforms created by alternative initiation. Has transcriptional repression activity. Mediates glucocorticoid-induced apoptosis. [Isoform Alpha-D1]: Has transcriptional activation activity. [Isoform Alpha-D2]: Has transcriptional activation activity. [Isoform Alpha-D3]: Has lowest transcriptional activation activity of all isoforms created by alternative initiation. Has transcriptional repression activity.
Synonyms: GR; GRL; GCCR; GCR; GCRST
Tractability: Small molecule: an approved drug acts on it; a structure with a bound ligand is known; a high-quality ligand is known; it has a high-quality binding pocket; it belongs to a druggable protein family. PROTAC: UniProt records ubiquitination sites on it; ubiquitination databases record sites on it; its protein half-life has been measured; a small molecule that binds it is known. Other modalities: a drug acting on it is in phase 2 or 3 trials.
Target class: Nuclear hormone receptor subfamily 3 group C member 1; Nuclear hormone receptor subfamily 3 group C; Nuclear receptor; Transcription factor; Nuclear hormone receptor subfamily 3
Chemical probes: AL-43 (high quality), BI 653048 (high quality), BMS-791826, CHEMBL1094208, FLUTICASONE FUROATE, FLUTICASONE PROPIONATE, PD080793, PD080841, PD080963, PD081261, PD081372, PD081723, PD081769, PD082117, PD082367, PD082672, PD082742, PD083486, PD083694, PD083700, and 16 more
Safety:
Unwanted effects reported when the protein is acted on. In parentheses: how it was acted on, where the effect was seen, and who reports it.
increased blood pressure (Bowes et al. (2012): activation, immune, endocrine; Lynch et al. (2017): activation, acute dosing, nervous system, immune, endocrine)
insulin resistance (Lynch et al. (2017): activation, acute dosing, nervous system, immune, endocrine; Bowes et al. (2012): activation, immune, endocrine)
osteoporosis (Lynch et al. (2017): activation, acute dosing, nervous system, immune, endocrine; Bowes et al. (2012): activation, immune, endocrine)
cardiac arrhythmia (activation; immune, endocrine; source: Bowes et al. (2012))
Decrease, Population growth rate (activation; source: AOP-Wiki)
decreased blood potassium (inhibition, acute dosing; nervous system, immune, endocrine; source: Lynch et al. (2017))
decreased inflammation (activation, acute dosing; nervous system, immune, endocrine; source: Lynch et al. (2017))
decreased memory (inhibition, acute dosing; nervous system, immune, endocrine; source: Lynch et al. (2017))
decreased muscle mass (activation, acute dosing; nervous system, immune, endocrine; source: Lynch et al. (2017))
decreased pain (activation, acute dosing; nervous system, immune, endocrine; source: Lynch et al. (2017))
decreased plasma potassium (activation; immune, endocrine; source: Bowes et al. (2012))
Decreased sperm quantity or quality in the adult, Decreased fertility (inhibition; source: AOP-Wiki)
decreased wound repair (activation, acute dosing; nervous system, immune, endocrine; source: Lynch et al. (2017))
edema (inhibition, acute dosing; nervous system, immune, endocrine; source: Lynch et al. (2017))
endometrial thickening (inhibition, acute dosing; nervous system, immune, endocrine; source: Lynch et al. (2017))
fatigue (inhibition, acute dosing; nervous system, immune, endocrine; source: Lynch et al. (2017))
glaucoma (activation; immune, endocrine; source: Bowes et al. (2012))
hyperglycaemia (activation; immune, endocrine; source: Bowes et al. (2012))
hypoglycaemia (inhibition; immune, endocrine; source: Bowes et al. (2012))
immunosuppression (activation; immune, endocrine; source: Bowes et al. (2012))
impaired, Fertility (activation; source: AOP-Wiki)
Increase, hypertension (activation; source: AOP-Wiki)
increased blood glucose (activation, acute dosing; nervous system, immune, endocrine; source: Lynch et al. (2017))
increased body weight (activation; immune, endocrine; source: Bowes et al. (2012))
increased inflammation (inhibition, acute dosing; nervous system, immune, endocrine; source: Lynch et al. (2017))
increased memory (activation, acute dosing; nervous system, immune, endocrine; source: Lynch et al. (2017))
increased urinary sodium excretion (activation, acute dosing; nervous system, immune, endocrine; source: Lynch et al. (2017))
Increased, agitation (activation; source: AOP-Wiki)
Increased, depression (activation; source: AOP-Wiki)
Increased, Liver Steatosis (activation; source: AOP-Wiki)
and 5 more effects
Gene: Protein-coding gene on chromosome 5 (143,277,931 to 143,435,512, reverse strand). Ensembl gene ENSG00000113580.
Subcellular location: Cytoplasm (Isoform Alpha); Nucleus; Mitochondrion; Cytoplasm, cytoskeleton, spindle; Cytoplasm, cytoskeleton, microtubule organizing center, centrosome; Chromosome; Nucleus, nucleoplasm; Nucleus (Isoform Beta); Cytoplasm; Nucleus (Isoform Alpha-B)
Subcellular location (Human Protein Atlas): Cytosol; Nucleoplasm; Mitochondria
Pathways (Reactome):
Gene expression (Transcription): FOXO-mediated transcription of oxidative stress, metabolic and neuronal genes; Nuclear Receptor transcription pathway; Regulation of NPAS4 gene transcription; Regulation of RUNX2 expression and activity
Cellular responses to stimuli: HSP90 chaperone cycle for steroid hormone receptors (SHR) in the presence of ligand
Disease: Potential therapeutics for SARS
Metabolism of proteins: SUMOylation of intracellular receptors
Signal Transduction: PTK6 Expression
Gene Ontology:
Molecular function: core promoter sequence-specific DNA binding; DNA-binding transcription activator activity, RNA polymerase II-specific; DNA-binding transcription factor activity; DNA-binding transcription repressor activity, RNA polymerase II-specific; Hsp90 protein binding; nuclear receptor activity; protein binding; protein kinase binding; RNA polymerase II cis-regulatory region sequence-specific DNA binding; RNA polymerase II transcription regulatory region sequence-specific DNA binding; sequence-specific double-stranded DNA binding; steroid binding; steroid hormone binding; TBP-class protein binding; DNA-binding transcription factor activity, RNA polymerase II-specific; estrogen response element binding; nuclear glucocorticoid receptor activity; DNA binding; identical protein binding; nuclear steroid receptor activity; promoter-specific chromatin binding; sequence-specific DNA binding; zinc ion binding
Biological process: cellular response to dexamethasone stimulus; cellular response to glucocorticoid stimulus; cellular response to steroid hormone stimulus; cellular response to transforming growth factor beta stimulus; negative regulation of DNA-templated transcription; negative regulation of transcription by RNA polymerase II; positive regulation of miRNA transcription; positive regulation of transcription by RNA polymerase II; regulation of DNA-templated transcription; nuclear receptor-mediated steroid hormone signaling pathway; regulation of transcription by RNA polymerase II; signal transduction; astrocyte differentiation; microglia differentiation; motor behavior; motor neuron apoptotic process; neuroinflammatory response; nuclear receptor-mediated corticosteroid signaling pathway; nuclear receptor-mediated glucocorticoid signaling pathway; positive regulation of DNA-templated transcription; response to glucocorticoid; response to ketone; synaptic transmission, glutamatergic
Cellular component: cytoplasm; cytosol; mitochondrion; nuclear speck; nucleoplasm; nucleus; protein-containing complex; chromatin; chromosome; mitochondrial matrix; centrosome; membrane; spindle; synapse
Genetic constraint (gnomAD): Loss-of-function variants: 13 observed, 70.32 expected, observed/expected ratio (o/e) 0.18, 90% interval 0.12 to 0.29. The upper end of that interval is the gene's LOEUF score, 0.29, which puts it in group 1 of 6, group 1 being the genes least tolerant of losing a copy. Missense variants: 690 observed, 947.75 expected, observed/expected ratio (o/e) 0.73, 90% interval 0.68 to 0.77. Synonymous variants: 307 observed, 350.4 expected, observed/expected ratio (o/e) 0.88, 90% interval 0.8 to 0.96.
Homologues: Orthologues: chimpanzee NR3C1 (99% identical), macaque NR3C1 (99% identical), dog NR3C1 (93% identical), rat Nr3c1 (91% identical), mouse Nr3c1 (90% identical), pig NR3C1 (90% identical), guinea pig NR3C1 (89% identical), rabbit NR3C1 (88% identical), tropical clawed frog nr3c1 (65% identical), zebrafish nr3c1 (47% identical), Drosophila melanogaster ERR (13% identical). Paralogues in human: NR3C2 (38% identical), PGR (32% identical), AR (29% identical), ESR2 (16% identical), ESR1 (16% identical), ESRRA (15% identical), ESRRG (15% identical), ESRRB (15% identical).
Diseases named in the same sentence as NR3C1 in open-access papers:
NR3C1 is named in the same sentence as 381 diseases in open-access papers, as found by Europe PMC text mining. Sharing a sentence is not in itself a finding about the gene and the disease. The quoted sentences say what the papers report.
depression (257 papers, 2006 to 2026). "For cognition, one site NR3C1 cg24052866 interacted with depression symptoms (GDS) to be associated with all cognitive domains tested in AIBL." (PMID 40964007, 2025). "Increased methylation of the NR3C1 promoter has been associated with heightened vulnerability to depression following childhood maltreatment." (PMID 41373485, 2025). "Elevated methylation levels of nuclear receptor subfamily 3 group C member 1 (NR3C1) modulate GR expression, significantly increasing the risk of depression within 2 weeks of ACS." (PMID 41301929, 2025). "Assessments have indicated that hypermethylation of BDNF and NR3C1 is associated with an increased risk of depression, while the methylation profiles of DNMT1/3A, EZH2, and IL-6 correlate to the severity of anxiety." (PMID 39851502, 2025). "Epigenetic modifications of the NR3C1 gene (glucocorticoid receptor) have been associated with increased depression risk." (PMID 40563330, 2025). "GSK3β is closely associated with the AD proteins PS2 and MAPT and with the depression‐related proteins NR3C1 and DKK‐1." (PMID 37501340, 2024). "NR3C1 methylation emerges as a common theme, with some studies reporting higher methylation levels associated with childhood trauma and recurrent depression, while others found lower methylation levels in individuals with mood disorders." (PMID 38792892, 2024). "NR3C1 encodes the glucocorticoid receptor (GR), which seems to have its signalling disrupted in anxiety and depression disorders, particularly in the context of early traumatic events." (PMID 39257475, 2024). "For example, early life stress is associated with epigenetic alterations of the NR3C1 gene encoding the glucocorticoid receptor (GR), with subsequent glucocorticoid resistance and development of depression." (PMID 37614344, 2023). "It has been suggested that early life stress alters the HPA-axis regulation and increases the risk of depression through epigenetic modifications in the glucocorticoid receptor gene (NR3C1)." (PMID 34590201, 2023). "Studies have indicated an association between methylation of NR3C1 exon 1F, particularly CpG2 methylation, and depression." (PMID 38249586, 2023). "NR3C1 hypermethylation is also associated with many poor health outcomes including depression, borderline personality disorder, and cancer." (PMID 36779373, 2023). "Pb and depression were also jointly associated with the two primary factor scores explaining the most variability in NR3C1 methylation; NR3C1 scores were associated with some infant outcomes, including gestational age and asymmetric fetal growth." (PMID 34831923, 2021). "NR3C1 methylation has been associated with trauma and mental issues, including depression, post-traumatic stress, anxiety, and personality disorders." (PMID 33762648, 2021). "Specifically, we found that NR3C1 methylation signatures among the two primary factors (factors 1 and 2) were the most sensitive to depression and Pb exposures, though associations were marginally significant." (PMID 34831923, 2021). "Smoking and depression in pregnancy have also been associated with altered methylation of placental stress-related genes, such as NR3C1 and HSD11B2, which encodes the enzyme that inactivates cortisol." (PMID 33608499, 2021). "Our analysis showed an association between suggestive symptoms of depression, as evaluated by Beck scores ≥ 17, with increased methylation at NR3C1 40–47 1F CpGs sites." (PMID 33762648, 2021). "It was shown that being a victim of violence during pregnancy not only increases the risk of depression and anxiety symptoms in women after childbirth but is also associated with changes in the methylation level of NR3C1 and FKBP5." (PMID 32373361, 2020). "High levels of methylation in the GR gene (nuclear receptor subfamily 3, group C, member 1; NR3C1) have been associated with depression and cardiovascular risk." (PMID 32218512, 2020).
depression (continued). "That is, ACS patients with NR3C1 hyper methylation, which was associated with cardiovascular risk markers, are more likely to also have depression." (PMID 32218512, 2020). "Higher NR3C1 methylation status was associated with depression and several cardiovascular risk markers at baseline." (PMID 32218512, 2020). "Recently, our study group found that higher DNA methylation of NR3C1 was independently associated with depressive disorder at the early phase of ACS13." (PMID 32218512, 2020). "In girls only, elevated NR3C1 methylation was associated with higher anxious-depressed symptoms and mediated the association between maternal depression and child symptoms." (PMID 31438539, 2019). "In adolescent males, increased NR3C1 exon 1F methylation was associated with stressful experiences such as being bullied, lacking friends and internalizing symptoms, as assessed by a depression scale." (PMID 31019524, 2019). "The stressors used in this study reduced Fkbp5 and Nr3c1 gene expressions in hippocampus associated with emotionality and reward pathways and reveals a role for CB2Rs in the mouse models of depression." (PMID 30042304, 2018). "For instance, adverse early experiences (e.g., low maternal care, abuse) can affect glucocorticoid receptor (GR) gene (NR3C1) expression, which stably predisposes one to anxiety and depression." (PMID 30323739, 2018). "The polymorphisms, methylation and expression of the NR3C1 gene have been indicated to be associated with depression and especially related to stress." (PMID 30042304, 2018). "In a study of 482 mother–term-born infant pairs (13.7% of whom had depression and/or anxiety), maternal depression was associated with increased methylation of the NR3C1 CpG2 site." (PMID 27918480, 2016). "Hit one represents polymorphisms in the AR, BDNF, 5HTTLPR, FKBP5, and NR3C1, which independently increase the risk of developing depression, AUDs, and suicidal behavior in men." (PMID 28096796, 2016). "Methylation of a second CpG site located in the NR3C1 exon 1E promoter region was also associated with depression symptoms, with methylation at both sites inversely associated with health related quality of life." (PMID 27918480, 2016). "Three other single nucleotide polymorphisms [SNPs (BclI, N363S, and ER22/23EK)] of NR3C1 were also associated with the increased recurrence of depressive disorders." (PMID 28096796, 2016). "Building on our previous work on reversal by maternal stroking of behavioral outcomes associated with prenatal depression and anxiety, we now show a reduction of NR3C1 gene methylation associated with maternal stroking." (PMID 25942041, 2015). "In conclusion, a multivariate study analyzing the role of genetic variants in the NR3C1 gene was performed in patients with asthma, with particular emphasis on the intensity of their depression, anxiety and shortness of breath." (PMID 25009637, 2014). "NR3C1 polymorphisms and haplotypes are general modulating factors of the level of depression, shortness of breath and anxiety, which significantly predispose patients with asthma to the development of affective disorders and anxiety." (PMID 25009637, 2014). "A total of 24 NR3C1 gene variants were detected for each of the tested variables (depression, state and trait anxiety and breathlessness)." (PMID 25009637, 2014). "The aim of this study was to investigate polymorphisms within the NR3C1 gene and their role in the susceptibility to recurrent depressive disorder (rDD)." (PMID 23073785, 2013). "Data obtained in our study corroborated previous results on involvement of NR3C1 polymorphisms in depression risk in Caucasian population." (PMID 23073785, 2013). "The NR3C1 gene is suggested to be a candidate gene affecting depressive disorder risk and management." (PMID 23073785, 2013).